EEF2K (eukaryotic elongation factor 2 kinase)
Diseases named in the same sentence as EEF2K in open-access papers (continued):
Sharing a sentence is not in itself a finding about the gene and the disease.
pancreatic cancer (8 papers, 2014 to 2025). "Our study sheds light on these mechanisms, showing that M2 macrophages promote a tumor-supportive environment by inducing increased levels of eEF2K in pancreatic cancer cells." (PMID 40624025, 2025). "In the current study, we further showed that the inhibition of eEF2K enhances the cytotoxic effects of gemcitabine in pancreatic cancer cells." (PMID 40624025, 2025). "From the earlier research study, it was proven that eEF2K was overexpressed in pancreatic cancer, and it was a crucial marker related to the low survival rate." (PMID 40567376, 2025). "This loop perpetuates M2-TAMs accumulation, further inducing eEF2K and promoting pancreatic cancer growth and progression." (PMID 40624025, 2025). "Overall, our results demonstrate that eEF2K mediates interactions between pancreatic cancer cells and TAMs through MCP-1/Gas6 signaling and exosomal communication, promoting tumor growth and progression." (PMID 40624025, 2025). "Consistent with eEF2K induction, macrophages induced mesenchymal-like morphological changes in pancreatic cancer cells, suggesting the induction of epithelial-mesenchymal transition (EMT) due to bidirectional interactions between these cells." (PMID 40624025, 2025). "Our results showed high eEF2K expression in pancreatic cancer cell lines, with weak expression in normal human pancreatic ductal epithelial (HPDE) cells." (PMID 40624025, 2025). "We further assessed eEF2K protein expression in pancreatic cancer cell lines, normal pancreatic epithelial cells, and patient tissue samples using Western blot and immunohistochemistry." (PMID 40624025, 2025). "Given the multifaceted oncogenic role of eEF2K in solid tumors, we investigated its role in pancreatic cancer tumorigenesis and the TME." (PMID 40624025, 2025). "We demonstrate for the first time that bidirectional interaction between pancreatic cancer cells and macrophages leads to upregulation of eEF2K signaling axis, which contributes to PDAC cell proliferation, migration, invasion, and accumulation of M2-type TAMs." (PMID 40624025, 2025). "The elongation factor-2 kinase (eEF-2K) regulates the invasive phenotype of pancreatic cancer cells by activating a signaling axis consisting of tissue transglutaminase (TG2) and the β1 integrin/uPAR/MMP-2 complex as well as a decrease in SRC activity." (PMID 31336983, 2019). "Therefore, eEF2K emerges as a promising therapeutic target for pancreatic cancer, with the potential to modulate interactions within the TME interactions and improve patient outcomes." (PMID 40624025, 2025). "However, further investigations are needed to elucidate the precise role of eEF2K in pancreatic cancer models." (PMID 40624025, 2025). "From the recent research, overexpression of eEF2K was demonstrated in pancreatic cancer." (PMID 40567376, 2025). "The further evaluation of these complex natural products or related analogues in vitro and in vivo could prove to be helpful for the development of eEF2K inhibiting anticancer agents, perhaps especially for pancreatic cancers." (PMID 33673713, 2021). "Whether NRF2 affects eEF2K phosphorylation levels in pancreatic cancer cells remains to be determined." (PMID 34247201, 2021). "Ashour and colleagues reported an overexpression of EEF2K in pancreatic cancer." (PMID 31266475, 2019). "Therefore, targeting the eEF2K/TAM axis may offer a novel therapeutic strategy to improve the survival outcomes of pancreatic cancer patients." (PMID 40624025, 2025). "The regulation of PP2A by eEF2K may contribute to its oncogenic role in pancreatic cancer." (PMID 40624025, 2025). "Furthermore, eEF2K is highly expressed in pancreatic cancer (PaCa) and acts to inhibit apoptosis." (PMID 33673713, 2021). "Thus, eEF-2K could represent a novel potential therapeutic target in pancreatic cancer." (PMID 25215932, 2014).
pancreatic cancer (continued). "In our present study, Kaplan-Meier survival analysis showed that pancreatic cancer patients with elevated levels of TAMs (indicated by the expression of CD163, CD204, and CD206) or eEF2K, as well as those expressing both CD68 and eEF2K, have poorer overall survival." (PMID 40624025, 2025). "Finally, the reported efficacy of 30 for reducing pancreatic tumors in vivo without overt effects on normal tissue offers more validation for both this compound and eEF2K as a molecular target for future drug development." (PMID 33673713, 2021).
depression (7 papers, 2019 to 2025). "Results from mouse models of EEF2K, which encodes a kinase associated with protein synthesis elongation, have postulated associations of this gene with synaptic plasticity, learning and memory, atherosclerosis-mediated cardiovascular disease, and depression." (PMID 33819264, 2021). "Further studies in rodents with depression-like phenotypes are needed to ascertain the role of eEF2K and 4E-BPs in the antidepressant-like effects of (R,S)-ketamine and its metabolites." (PMID 33963284, 2022). "Studies indicate that eEF2K is expressed in neurons and may contribute to processes such as learning, memory, and depression." (PMID 39180059, 2024). "Both pathways inhibit eEF2K activity by phosphorylation of eEF2K on e366, resulting in dephosphorization of eEF2 Thr56, suggesting that eEF2 may be a promising therapeutic target for the treatment of depression." (PMID 36059987, 2022). "The eEF2K-cKI mice exhibit learning and memory impairments, and robust apathy-like phenotype without other despair/depression-like behaviors." (PMID 41392093, 2025).
hepatocellular carcinoma (7 papers, 2017 to 2024). A malignant tumor that arises from hepatocytes. "In hepatocellular carcinoma, eEF2K promotes angiogenesis via the PI3K/Akt and STAT3 signaling pathways." (PMID 39592671, 2024). "For example, knockdown of eEF2K was found to prevent tumor progression and angiogenesis of hepatocellular carcinoma via the PI3K/Akt and STAT3 signaling pathway." (PMID 33673713, 2021). "One of the many cancer types that eEF2K is overexpressed in is hepatocellular carcinoma (HCC)." (PMID 33673713, 2021). "In hepatocellular carcinoma, eEF2K promotes angiogenesis through PI3K/Akt and STAT3 signaling." (PMID 33673713, 2021). "Huanglian Jiedu decoction (HLJDD), a traditional Chinese Medicinal (TCM), could activate AMPK signaling and further inhibit the mTOR pathway, thus reducing the phosphorylation of eEF2K in hepatocellular carcinoma (HCC) cells." (PMID 33673713, 2021).
Hypertension (5 papers, 2016 to 2023). The presence of chronic increased pressure in the systemic arterial system. "For example, eEF2K has been shown to mediate reactive oxygen species (ROS)-dependent vascular inflammation and is partly responsible for hypertension via propagating vascular hypertrophy and endothelial dysfunction in rats." (PMID 34532346, 2021). "Eukaryotic Elongation Factor 2 Kinase (eEF2K) is pivotal in CD8+ T cells and has important implications in vascular dysfunction and inflammation-related diseases such as hypertension." (PMID 37875468, 2023). "eEF2K (NM_007908.4) is a Ca2+/calmodulin-dependent protein kinase that regulates JNK (c-jun N-terminal kinase) and NF-κB (nuclear factor-kappa B) p65 phosphorylation as well as reactive oxygen species (ROS) production and also affects the development of hypertension." (PMID 27020049, 2016).
Cognitive impairment (4 papers, 2022 to 2026). Abnormal cognition is characterized by deficits in thinking, reasoning, or remembering. "Here, we investigated the roles of neuronal eukaryotic elongation factor 2 (eEF2) phosphorylation (by its kinase eEF2K) in AD-associated cognitive deficits and NPS." (PMID 41836505, 2026). "Our data suggested that eEF2K signaling dysregulation mediates DS‐associated synaptic and cognitive impairments." (PMID 38934363, 2024). "Our findings support the hypothesis that eEF2K signaling dysregulation and related mRNA translation deficits play a crucial role in synaptic and cognitive impairments associated with DS." (PMID 38934363, 2024). "The current study, mainly by using rodent models of DS, aims to test the central hypothesis that eEF2K–eEF2 signaling dysregulation plays an important role in DS‐associated cognitive deficits and synaptic failure with aging." (PMID 38934363, 2024). "Inhibition of eEF2 phosphorylation through suppression of eEF2K in DS model mice improved multiple aspects of DS‐associated pathophysiology including de novo protein synthesis deficiency, synaptic morphological defects, long‐term synaptic plasticity failure, and cognitive impairments." (PMID 38934363, 2024). "In conclusion, suppression of eEF2K improved multiple pathophysiology in Dp16 mice including protein synthesis deficits, synaptic failure, and cognitive impairments." (PMID 38934363, 2024). "From a translational perspective, inhibition of eEF2K and eEF2 phosphorylation can be an appealing therapeutic approach for aging‐related cognitive deficits in DS." (PMID 38934363, 2024). "In summary, suppression of eEF2K can restore eEF2 phosphorylation levels and alleviate cognitive deficits in the Ts65Dn DS mouse model." (PMID 38934363, 2024). "Taken together, these studies suggest that eEF2K suppression confers protective effects against cognitive deficits displayed in aged and AD model mice." (PMID 36158543, 2022). "Previous work from our lab showed that either knockdown or knockout of eEF2K in AD mouse models could alleviate cognitive deficits in a protein synthesis‐dependent manner and possibly through the NRF2‐mediated antioxidant response." (PMID 38934363, 2024). "Importantly, restoration of eEF2 phosphorylation by suppression of eEF2K could alleviate multiple pathophysiological abnormalities and improve aging‐related cognitive deficits in two different lines of a DS mouse model." (PMID 38934363, 2024). "Finally, as a proof‐of‐concept study, we showed that the small‐molecule eEF2K inhibitor A484954 could rescue cognitive impairments and synaptic failure in DS model mice, suggesting targeting the eEF2K signaling could be a feasible therapeutic strategy for aging‐related cognitive impairments in DS." (PMID 38934363, 2024). "To address this question, here we knockout eEF2K completely in the APP/PS1 AD model mice and investigated whether AD-related cognitive impairments would be fully reversed." (PMID 36158543, 2022). "In brief, treatment of eEF2K inhibitors could decrease eEF2 phosphorylation, boost de novo protein synthesis, reverse synaptic impairments, and rescue cognitive deficits in Ts65Dn DS model mice." (PMID 38934363, 2024).
epilepsy (4 papers, 2016 to 2022). A brain disorder characterized by episodes of abnormally increased neuronal discharge resulting in transient episodes of sensory or motor neurological dysfunction, or psychic dysfunction. "We recently demonstrated that eEF2K deletion in mice caused an enhancement in GABAergic transmission that was accompanied by an increased resistance to epilepsy." (PMID 34980259, 2022). "eEF2K-deficient mice display a more robust GABAergic signaling and exhibit a rescue effect on epilepsy symptoms, suggesting that pharmacological or genetic inhibition of eEF2K could potentially counteract disease phenotypes." (PMID 34532346, 2021). "Accordingly, we showed that eEF2K deletion, in a mouse model of human epilepsy, the Synapsin1 knock out mice, rescued the epileptic phenotype." (PMID 34980259, 2022). "Our data indicate that pharmacological inhibition of eEF2K could represent a novel therapeutic intervention for treating epilepsy and related comorbidities in the Dravet syndrome." (PMID 34980259, 2022). "We found a strong increase of number of spikes measured in 24 h in Scn1a ± mice after the thermal stress but not in the Scn1a ± eEF2K−/− mice, suggesting that eEF2K deficiency reduced the susceptibility to epilepsy of the Scn1a ± mice." (PMID 34980259, 2022). "Indeed, we demonstrated that genetic and pharmacological eEF2K inhibition rescued the epileptic phenotype in a genetic animal model of epilepsy, the Synapsin1 knock out mice." (PMID 34980259, 2022). "Moreover, the pharmacological and genetic inhibition of eEF2K was recently reported to be able to reverse the epileptic phenotype in a mouse model of human epilepsy." (PMID 27826228, 2016). "Chronically increased neuronal excitation might lead to the excitatory synapse dependent activation of the eEF2K/eEF2 pathway and the subsequent dampening of the GABAergic synapses would further increase network activity, thereby aggravating the epilepsies in the Scn1a ± mice." (PMID 34980259, 2022).
glioblastoma (4 papers, 2016 to 2025). The most malignant astrocytic tumor (WHO grade IV). "Previously, studies have shown that eEF2K is overexpressed in glioblastoma multiforme and plays a role in cell migration, invasion, and apoptosis in combination with temozolomide." (PMID 40725039, 2025). "Furthermore, we identified for the first time the binding interaction between FOXM1, AXL, and eEF2K within the glioblastoma concept." (PMID 40725039, 2025).
memory impairment (4 papers, 2023 to 2025). "In summary, we have employed multiple approaches to fully demonstrate the target role of eEF2K in the process of learning and memory impairment caused by ACR, and further innovatively elucidated its mechanism of action, filling a gap in the research field." (PMID 39180059, 2024). "This suggests that eEF2K has a hub function in the process of learning and memory impairment caused by ACR and is an important target protein." (PMID 39180059, 2024). "This indicates that eEF2K affects ether lipid metabolism through Lpcat1, thereby playing a role in the process of learning and memory impairment caused by ACR." (PMID 39180059, 2024). "Therefore, we used eEF2K-KO mice to explore whether eEF2K is an important target in the process of learning and memory impairment caused by ACR." (PMID 39180059, 2024). "However, it is still unclear whether eEF2K is involved in the process of learning and memory impairment caused by ACR." (PMID 39180059, 2024). "A recent study shows that suppressing the eEF2K mRNA translation factor alleviates learning and memory impairments in aged mice." (PMID 39180059, 2024). "Given the crucial role of new protein synthesis in long-term memory, eEF2K presents a novel research avenue for investigating learning and memory impairment in brain neurons." (PMID 39180059, 2024). "In summary, eEF2K as a pivotal treatment target in the mechanisms underlying ACR-induced learning and memory impairment, and studies have shown that it provides robust evidence for potential clinical interventions targeting ACR-induced impairments." (PMID 39180059, 2024). "We validated the role of eEF2K in the process of ACR-induced learning and memory impairment through both in vitro and in vivo experiments, and elucidated the possible mechanisms of action." (PMID 39180059, 2024). "Additionally, we proposed for the first time that eEF2K can serve as an important target in ACR-induced learning and memory impairment." (PMID 39180059, 2024). "As eEF2K is a small molecule kinase, the development of inhibitors targeting eEF2K may become a novel strategy for the prevention or treatment of ACR-induced learning and memory impairment." (PMID 39180059, 2024).
atherosclerosis (3 papers, 2014 to 2022). A disease characterized by the build-up of fatty material and calcium deposition in the arterial wall resulting in partial or complete occlusion of the arterial lumen. "Our findings revealed a significant reduction in atherosclerosis in mice who received a transplant of bone marrow reconstituted from eef2k-KI mice, and thus revealed eEF2K as a potential target for therapy." (PMID 25475470, 2014). "After recovery, these chimeras were fed a high-fat diet to induce atherosclerosis and mice with mutant eEF2K had a greatly reduced level of atherosclerosis." (PMID 25475470, 2014). "EEF2K is also demonstrated to be responsible for atherosclerosis in one study." (PMID 36685865, 2022). "Based on the premise that macrophage survival contributes to their persistence in the intima, we postulated that blocking eEF2K activity might suppress development of atherosclerosis." (PMID 25475470, 2014). "Because eEF2K activity in cells of the hematopoietic compartment contributes to atherosclerosis development, drugs inhibiting eEF2K might have a beneficial effect in treatment of atherosclerosis." (PMID 25475470, 2014). "Finally, it will be important to begin testing eEF2K inhibitors in vivo for their effectiveness in blocking atherosclerosis development." (PMID 25475470, 2014). "Although our studies show a partial block of atherosclerosis when eEF2K activity is suppressed, eEF2K inhibitors might become even more valuable when used together with other atherosclerosis drug therapies." (PMID 25475470, 2014). "Impairment of eEF2K activity suppressed the prosurvival effect of oxLDL, suggesting eEF2K could influence the effect of macrophages on atherosclerosis." (PMID 25475470, 2014).
dementia (3 papers, 2025 to 2026). Loss of intellectual abilities interfering with an individual's social and occupational functions. "Our findings present direct evidence supporting the pathophysiological role of aberrant eEF2K/eEF2 signaling in brain function and help provide insight into novel mechanisms and therapeutic avenues for neuronal diseases characterized by dementia and neuropsychiatric symptoms." (PMID 41392093, 2025). "Our findings indicate the therapeutic potential of targeting the eEF2K signaling in the treatment of dementia and NPS in AD and related dementias (ADRDs)." (PMID 41836505, 2026).
esophageal squamous cell carcinoma (3 papers, 2021 to 2025). Esophageal squamous cell carcinoma (ESCC) is a type of esophageal carcinoma (EC) that can affect any part of the esophagus, but is usually located in the upper or middle third. "eEF2K is a useful therapeutic target as it has been identified as an indicator of stomach adenocarcinoma and decreased expression of eEF2K in esophageal squamous cell carcinoma facilitated greater apoptosis." (PMID 41327312, 2025). "The growth of esophageal squamous cell carcinoma (ESCC) is facilitated by YY1BM, a 21 aa micropeptide encoded by LINC00278, which blocks the connection between YY1 and androgen receptor (AR), reducing eEF2K production through the AR signalling pathway." (PMID 38622617, 2024). "In esophageal squamous cell carcinoma (ESCC), eEF2k express higher than non-tumor tissues, and ablation of eEF2K correlated with slower migration and proliferation rate." (PMID 34532346, 2021).